IL6 (interleukin 6)
Diseases named in the same sentence as IL6 in open-access papers (continued):
Sharing a sentence is not in itself a finding about the gene and the disease.
tumor (continued). "A recent report described that IL-6 and HGF secreted by tumor neighbouring VAT induce the expression of the metastatic marker CD44v6 in CRC cells and the transition from an epithelial consensus molecular subtype (CMS2) towards a mesenchymal subtype (CMS4)." (PMID 36361914, 2022). "CAF IL-6 expression is upregulated in response to IL-1 secreted by malignant cells, whereas production of TGF-β (by tumor cells) downregulates CAF surface IL-1R, favoring increased matrix secretion by this CAF subtype." (PMID 35267539, 2022). "TAMs are known to contribute to tumor growth, infiltration, and neovascularization via multiple mechanisms, such as secretion of cytokines and growth factors—TGF-β, IL10, IL6, IL1β, pleiotrophin, and EGF." (PMID 35920986, 2022). "The IL6/JAK/STAT3 signaling pathway plays an essential role in the proliferation, survival, and invasion of tumor cells." (PMID 35799780, 2022). "MDSCs can also inhibit immune function to accelerate tumor progression, increase tumor cell stemness and angiogenesis, as well as promoting EMT through IL-6 secretion." (PMID 36226048, 2022). "The IL-6/JAK/STAT3 signaling pathway is hyperactivated in many cancer types and leads to a strong suppression of the anti-tumor immune response." (PMID 36387244, 2022). "IL-1β, IL-6, CXCL8, CXCL10, and vascular endothelial growth factor comprise the M2 TAMs that contribute to cancer metastasis, immune suppression, and tumor growth." (PMID 36239108, 2022). "The LTα, IL-6, and VEGF promote angiogenesis, which will ultimately contribute to tumor growth and spread." (PMID 35055124, 2022). "The PCR results showed that ALB, ANGPTL7, IL6, and NGB were down-regulated in the BC tumor tissues, and BLOC1S5-TXNDC5 was up-regulated in the BC tumor tissues." (PMID 35962042, 2022). "CD40 engagement on HRS cells increased both tumor growth and survival, upregulated CD54, CD80, and IRF4 expression, augmented the secretion of IL-8, TNF-α, IL-6, LT-α and CCL5, decreased Fas-mediated apoptosis and increased NF-kB activation." (PMID 35626032, 2022). "Increased/aberrant WNT signaling in the tumor cell usually leads to a great release of WNT ligands and proinflammatory mediators (i.e., IL-6 and MCP-1), which is sustained over time due to a self-feeding loop." (PMID 35742983, 2022). "Immune cells recognize tumor cell surface antigens and then initiate cellular immunity and kill tumor cells by secreting anti-tumor-related cytokines (INF-γ, TNF-α, and IL-6, etc.)and cell phagocytosis." (PMID 35386701, 2022). "M1-TAMs play a key role in killing tumor cells by producing reactive oxygen/nitrogen species (ROS/RNS) and pro-inflammatory cytokines such as IL-1β, IL-6, and TNF-α, and thus M1-TAMs are macrophages with anti-tumor effects." (PMID 35479325, 2022). "CML-MSCs enhance immunosuppressive MDSCs production and aggregation, promoting tumor progression via upregulating immunomodulatory arginase-1 (Arg-1), IL-6, IL-1β, COX-2, and TNF-α in MDSCs and inhibiting anti-tumor immunity." (PMID 35842634, 2022). "The enrichment of immunologic gene sets, such as IL2-STAT5 signaling, IL6-JAK-STAT3 signaling, and inflammatory responses, varied across the cancer types, resulting in two tumor clusters." (PMID 35794212, 2022). "IL-17, IL-21, IL-22, TNF-α and IL-6 are also produced in excess in individuals with CRC and synergistically promote tumor growth." (PMID 35739324, 2022). "The results revealed that the INTERFERON_GAMMA_RESPONSE pathway, the IL2_STAT5_SIGNALING pathway, the TNFA SIGNALING VIA NKFB pathway, the UV_RESPONSE_UP, IL6_JAK_STAT3_SIGNALING pathway, and the HYPOXIA pathway were upregulated in tumor-infiltrating cells." (PMID 35812372, 2022). "A large number of studies have shown that IL-6/JAK2/STAT3 signaling pathway is abnormally highly activated in many types of cancer and strongly inhibits anti-tumor immune response." (PMID 36591515, 2022).
tumor (continued). "IL-8, macrophage movement inhibitory factor, and fibrinolytic enzyme activator inhibitor 1 secreted by metastatic lung cancer cells can activate astrocytes that produce growth factors (IL-6, IL-1, and TNF-α), encouraging tumor growth." (PMID 35251014, 2022). "Through the production of IL6, CAFs induce the expression of CXCR7 through the STAT3/NFkB pathway in tumor cells, which is responsible for drug resistance." (PMID 36114508, 2022). "The 4T1-specific knockout of IL-6 led to a significant reduction in both M-MDSC and PMN-MDSC in all peripheral organs, and tumor=-infiltrating M-MDSC was also reduced in the 4T1-IL6-KO tumors." (PMID 36142210, 2022). "Tumor microenvironments in solid tumors are rich in many cytokines, including IL-1, IL-6, IL-4, IL-8, granulocyte-CSF, MF inhibitory cytokine-1 (MIC-1), and TGF-β, which can impair the anti-tumor immune responses and shield them from T-cell infiltration." (PMID 36627890, 2022). "All these data suggest that N6L can exert a pleiotropic effect on the tumour microenvironment and tumour cells in PDAC, compared to anti-IL-6 and other anti-angiogenic drugs." (PMID 36077801, 2022). "Most genes were highly enriched in tumor tissues, while only 4 genes including ELANE, IL6, IL1B and NLRP3 were upregulated in normal tissues." (PMID 36267972, 2022). "The secretion of IL-6, CXCL-9, and TGF-β by CAFs plays a significant inhibitory role in anti-tumor T cell response." (PMID 36209263, 2022). "Pro-inflammatory cytokines IL-6, IL-1β and TNF-α were found to be higher in tumor-control group compared to normal control animals." (PMID 35197512, 2022). "IL-6 also promotes the production of HIF-1α and enhances the self-regulation of Tregs in the process of tumor microenvironment (TME) formation." (PMID 35927985, 2022). "Unfortunately, EZH or HDAC suppression also induces M1 GAMs secreting IL-1β and IL-6, and activates STAT3 signals in GBM tumor cells, leading to an aggravated inflammatory response in the TME of GBM." (PMID 35572545, 2022). "We also found that IL-6 induced the expression of CSC- and EMT-related markers, while establishing an immunosuppressive tumor microenvironment." (PMID 36186905, 2022). "4T1 cells were injected into the mammary fat pad of mice and when the tumor reached to palpability, CM of activated RAW264.7 or IL-6 neutralized CM of activated RAW264.7 cells was administrated intra-tumorally and tumor growth was observed." (PMID 35300689, 2022). "Exosomal miRNA often targets distinct pathways such as CCL2, IL-6, IL-8, WNT, and PI3K and remodels the pro-malignant properties of tumor cells." (PMID 35327514, 2022). "Macrophages secrete various growth factors such as TGF-β, VEGF, PDGF, cytokines such as M-CSF and interleukins, chemokines such as IL-6, IL-10, CCL2, and CXCL, and enzymes such as MMPs which promote tumor growth." (PMID 36679900, 2022). "In patients with cancer, proinflammatory cytokines such as interleukin (IL)-1, IL-6, tumor necrosis factor alpha (TNF-α), interferon-alpha (IFN-α), and interferon-gamma (IFN-γ) are released by the tumor or the host’s immune system in reaction to the tumor." (PMID 35455957, 2022). "Tumor-derived MSCs secrete large amounts of IL-6 and IL-8 to stimulate M2 macrophage polarization, which enhances the EMT of gastric cancer, thus promoting migration and invasion of tumor." (PMID 35846142, 2022). "Siltuximab, which is a neutralizing anti-IL-6 antibody, delayed engraftment of MCF-7 humanized xenograft tumors and elicited tumor xenograft regression in tumors." (PMID 35924148, 2022). "Compared with the Puget 0 grade tumor group, the expression of IL1A and IL6 in the Puget 2 tumor group was significantly increased." (PMID 36389809, 2022). "γδTreg cells were found to impair DC maturation and function and CD8+T cell-mediated anti-tumor function in cancer patients via TGF-β, IL-6 or IL-10 dependent or independent manner." (PMID 35747139, 2022).
tumor (continued). "Regarding the evidence that IL-6 signaling elicits the AnxA1/FPR1 axis leading in TNBC cells, we tested the in vivo effect of this receptor inhibition on tumor growth and fibroblast migration." (PMID 35626741, 2022). "TNBC-derived IL6 induces CCL5 expression in stromal lymphatic vessels of the lung and lymph nodes through STAT3-AP1 signaling, resulting in tumor extravasation and colonization." (PMID 36612175, 2022). "S. mutans infection induced IL6 expression in cancer cells; it also significantly elevated IL-6 levels in the cell culture supernatant and serum of 4-NQO-induced tumor model." (PMID 36186905, 2022). "CD163+ TAMs produced tumor-supporting cytokines (IL-6 and CXCL2) activated STAT3 in tumor cells and supported tumor progression." (PMID 36686729, 2022). "Then, we assessed the expression levels of IL-6, Laminin α5, and phosphorylated FAK in tumor tissues of a total of six patients with osimertinib resistance." (PMID 35197546, 2022). "In vivo, tramadol administration decreased the expression of inflammatory cytokines such as IL-6 and tumor necrosis factor-α (TNF- α), which are involved in tumor growth and invasion, and maintained NK cell activity, unlike morphine." (PMID 35223475, 2022). "Mechanistically, EREG appeared to be essential for normal fibroblast to CAF transformation and essential for the induction of tumor cell EMT in a JAK2-STAT3- and IL-6-dependent manner." (PMID 35844493, 2022). "The excessive activity of the NF-κB/IL-6/STAT3 axis results in c-Myc and cyclin D1 overexpression, metabolic disorders, tumor growth, progression, and chemoresistance acquisition." (PMID 35884974, 2022). "The activation of REG3A will enhance JAK2/STAT3 pathway, amplify the carcinogenic effect of IL-6/JAK2/STAT3, and ultimately leads to excessive PC cell proliferation in vitro and in vivo and tumor formation." (PMID 36591515, 2022). "EMT is known to play a central role in inducing resistance of tumor cells to irradiation, and it is regulated by a variety of molecular mechanisms containing TGF-β, Wnt/β-catenin, PI3K/AKT, Notch, NF-κB, IL-6/STAT3, non-coding RNAs and so on." (PMID 35251963, 2022). "One of the key signaling pathways controlling this phenomenon is the IL-6/JAK/STAT3 axis, which enhances tumor proliferation and cell metabolism by upregulating this signaling pathway." (PMID 36091125, 2022). "In colorectal cancer, MSCs release PGE-2 in response to IL-1 secreted by tumor cells, PGE-2 in an autocrine fashion promotes the expression of IL-8, IL-6, CXCL1, RANTES, and GRO-α, which together stimulate the formation of CSCs." (PMID 35251985, 2022). "Myeloid-derived suppressor cells are attracted by inflammatory cytokines (e.g., IL-1β, IL-6, PGE2, and tumor growth factors), increasing their production of S100/calgranulins." (PMID 36411489, 2022). "PCR results showed that HPP promoted the expression of IL-1β, IL-6 and TNF-α mRNA in macrophages in the tumor microenvironment." (PMID 35603205, 2022). "TAMs secrete cytokines (IL6, IL10, etc.)and exosomes (miR-21-5p, miR-155-5p, etc.)through NFKB1 signaling pathway, STAT3 signaling pathway, and other pathways to act on tumor cells and immune cells, regulating the process of CRC." (PMID 35186730, 2022). "IL-1 and IL-6 can regulate the carcinogenic transcription factors NF-κB and STAT3, which play important biological functions and can accelerate tumor growth and progression." (PMID 35634419, 2022). "Estimation of common cytokines like IL-6, TNF-α, and IL-1β in brain samples showed a rise in cytokine levels in CMF treated tumor-bearing animals." (PMID 35197512, 2022). "For their reciprocal interaction with TAMs, tumor cells were found to secrete some signal molecules and cytokines such as CSF1 and IL-6 required for TAMs activation." (PMID 35493456, 2022). "In the tumor microenvironment (TME), IL-6 is among the most expressed cytokines in the inflammatory stroma subtype in patient tumors." (PMID 35993361, 2022).
tumor (continued). "CAFs have been identified as an important source of IL-6 recently and IL-6 mediated STAT3 activation in CAFs facilitates CRC tumor development." (PMID 35463300, 2022). "LLL12, prevents IL-6-induced STAT3 phosphorylation at Y705, and demonstrates efficacy in vivo in a TNBC MFP mouse model with a concomitant reduction in tumor volume and pSTAT3 expression." (PMID 35371975, 2022). "In ESCC, CAFs generate M-MDSCs by the secreted IL6 and exosomal microRNA-21, and the CAF-induced M-MDSCs confer chemoresistance on tumor cells." (PMID 36211375, 2022). "In the tumor microenvironment, TNF-α was upregulated and IL-6 was down-regulated significantly in nanovaccine group." (PMID 35418151, 2022). "The blockade of the constitutive expression of STAT3 in tumor reduced the expression of VEGF, IL-6, and IL-10, which neutralized the inhibitory effect of dendritic cell maturation." (PMID 35936759, 2022). "Elevated serum levels of IL-6 have been detected in patients with untreated metastatic or CRPC, thus negatively correlating with tumor survival and response to chemotherapy." (PMID 36338516, 2022). "ING5 suppresses proliferation, migration, invasion and tumor growth of various cancer cells via the suppression of EGFR/PI3K/Akt, IL-6/STAT3, Akt/NF-κB/NF-κB/MMP-9 or IL-6/CXCL12 pathway." (PMID 36425530, 2022). "Secretion of IL-6, CXCL1 and the prostaglandin-regulating enzyme COX-2 by stromal CAFs promotes tumor growth in breast and ovarian cancer." (PMID 35267539, 2022). "Immunohistochemistry was performed to assess IL6 and LIF expression in both the tumor cells and surrounding stroma." (PMID 36230597, 2022). "IL-6 was used to induce STAT3 activation, resulting in the abolishment of the anti-tumor effect of Stattic in PCCs." (PMID 35288541, 2022). "Mechanistically, ligustilide impaired the secretion of the signals from tumor cells via inhibiting the YAP nuclear transcription and expression to inactive the IL-6/STAT3 signaling." (PMID 36615387, 2022). "As in other tumor types, a pro-tumoral cytokine network induced by CD4+ T and myeloid-lineage cells in the TME, including prostaglandin E2 (PGE-2), IL-6, IL-10, and TGF-β, exacerbates the repression of effector CD8+ T cell response and induces Tregs." (PMID 35920986, 2022). "In vitro treatment with trabectedin decreased the production of CCL2, CXCL8, IL-6, VEGF and PTX3 by myxoid liposarcoma (MLS) primary tumor cultures and/or cell lines, and freshly isolated ovarian cancer cells from ascites." (PMID 35299737, 2022). "MDSCs release IL-10 to downregulate IL-12 secretion by macrophages while macrophages in turn induce MDSCs to increase IL-10 which decreases IL-6 and TNF-α in macrophages and therefore skewing the immunity towards tumor promoting type 2 response." (PMID 35183252, 2022). "IL-6 is known to lead to the activation of STAT3, which is a proto-oncogene that can induce tumor formation." (PMID 35205671, 2022). "HSP72 and HSP105 on the TEX surface were found to induce DCs to produce increased IL-6 in a TLR2- and TLR4-dependent manner, which in turn promoted tumor invasion by increasing STAT3-dependent matrix metalloproteinases 9 transcription activity in tumor cells." (PMID 35163380, 2022). "For the first time, the correlation of the salivary levels of TNF-α, IL-1β, and IL-6 with HER2 status, MCP-1, IL-1β, IL-2, and IL-4 with the hormonal status of the tumor was shown." (PMID 36286034, 2022). "Once in the site, MDSCs stimulate the migration of tumor cells by secreting TNFα, CXCL2, TGFβ, IL-6 and CCL2." (PMID 35158779, 2022). "KW6002 administration in tumor-bearing mice limited indicators of renal toxicity (KIM-1) and expression of the inflammatory cytokines Tnf and Il6 induced by cisplatin." (PMID 36377661, 2022).
tumor (continued). "Preclinical models have also correlated RFA-induced increases of inflammatory cytokines IL-6, HGF, and VGEF, to upregulation of downstream key proliferative pathways, and resultant accelerated distant tumor growth peaking 6h to 3d following ablation." (PMID 35857766, 2022). "Transforming growth factor-β (TGF-β) is the type of profibrogenic cytokine that can promote tumor invasion and metastasis by inducing EMT as well as promoting inflammatory responses by activating interleukin-1 (IL-1β) and interleukin-6 (IL-6) in monocytes." (PMID 36232707, 2022). "As an example, the prelecan in healthy endothelial cells inhibits IL-6 in the TME and prevents its tumor-promoting effects." (PMID 35884405, 2022). "More recently, Ham and co-workers confirmed the prominent role of IL-6 and TGF-β in tumours of the gastrointestinal tract, where these two factors induce resistance to chemotherapy and actinotherapy." (PMID 35055153, 2022). "Elevated IL-6 can stimulate the excessive activation of STAT3, including angiogenesis and tumor metastasis." (PMID 35672352, 2022). "Our results are consistent with the previous studies illustrating that levels of inflammatory-related factors, such as IL-6, would increase in CRC, and tumor recurrence is closely related to the expression of inflammatory factors." (PMID 35946886, 2022). "In line with this and our earlier findings demonstrating the necessity of IL-6, all three inhibitors abrogated the ability of EVsMMA-MRC5 to induce IL-6/JAK/STAT3 and TGFβ signaling in A549 tumor cells, along with EMT." (PMID 36266345, 2022). "First, PHLDA1 was positively correlated with the infiltration levels of a variety of immunocompetent tumor-infiltrating cells, including Act CD4, CD56dim, and Act DC, and 23 types of immune promoters, including IL6, NT5E, and TNFSF9." (PMID 36142223, 2022). "IL-6, IL-8 and VEGF play a crucial role in tumor microenvironment and represent key signals in the communication between adipose, cancer, endothelial and immune cells." (PMID 36358839, 2022). "Cancer cells release TGF-β that activates CAF, which then secretes various immunomodulatory chemicals, including IL-11, IL-6, and TGF-β, to not only inhibit anti-tumor immunity but also deposit increasing amounts of ECM." (PMID 36300110, 2022). "Tumor growth triggers an inflammatory response around the tumor, which induces the secretion of inflammatory cytokines, such as tumor necrosis factor-α (TNF-α), interleukin (IL)-6, and IL-1β17,18." (PMID 35388147, 2022). "A preclinical study shows that TJ-48 inhibits the production of IL-6, MCP-1, PYY, and GLP-1 and ameliorates cancer-induced anemia using a CT-26 tumor-bearing mouse cancer anorexia/cachexia model." (PMID 35736467, 2022). "Among these, the expressions of 3 genes (IL6, IL1B, and NLRP3) were found to be downregulated in the tumor group while others were upregulated compared to the adjacent nontumorous group." (PMID 35069975, 2022). "The combined use of an IL6-JAK-STAT3 signaling pathway inhibitor and paclitaxel reduced OC stem cell viability and suppressed tumor growth." (PMID 35585970, 2022). "Interleukins can have a wide variety of pro- or anti- tumor effects and many have been therapeutically targeted in CRC clinical trials including IL-2, IL-12, IL-11, IL-6, IL-α, and IL-1β." (PMID 35205776, 2022). "GBM tumor cells also foster pericytes and endothelial cells to produce more IL-10 and TGFβ by activating the IL-6/STAT3 signaling pathway, thus inciting tumor growth." (PMID 35572545, 2022). "By contrast, to control animals, the immunized mice demonstrated completely inhibited tumor growth for 24 days and a decreased production of the INF-γ, IL-6, and IL-1 proinflammatory cytokines." (PMID 36430792, 2022). "Further studies demonstrated that CQF significantly reduced IL-17A levels, which in turn inhibited NF-κB/IL-6/STAT3 signaling cascade, suppressed MMP9 expression and promoted tumor cell apoptosis." (PMID 35991881, 2022).